FOSL1 (FOS like 1, AP-1 transcription factor subunit)
Diseases named in the same sentence as FOSL1 in open-access papers (continued):
Sharing a sentence is not in itself a finding about the gene and the disease.
breast carcinoma (continued). "Together, our results indicate that in mammary tumor cells GATA3 directly activates the transcription of FOS to maintain their luminal and epithelial features while concurrently repressing the transcription of FOSL1 to suppress aberrant mesenchymal differentiation, i.e., inhibiting EMT." (PMID 37353480, 2023). "Moreover, the EMT-transformed breast cancer cells often accumulate FOSL1, regardless of their ER status, preparing for EMT and tumor dissemination." (PMID 35163444, 2022). "In addition, FOSL1 also mediates the dephosphorylation of proliferation and apoptosis bridging protein 15 (PEA15) by upregulating dual-specificity phosphatase 7 (DUSP7), which increases drug resistance in breast cancer." (PMID 36061185, 2022). "Interestingly, in basal-like and mesenchymal breast cancers the PI3K-AKT and MEK-ERK pathways are often activated, resulting in high levels of JUN and FOSL1, whereas luminal A breast cancers do not show activation of the ERK1/2 MAP-kinase pathway." (PMID 32350443, 2020). "Therefore, upregulation of FOSL1 mRNA alone may not be sufficient to predict survival for basal-like breast cancer." (PMID 37353480, 2023). "Although not as strong as the correlation between GATA3 and FOSL1, a positive correlation between GATA3 and FOS mRNA levels was also detected in human breast cancers." (PMID 37353480, 2023). "Conversely, FOSL-1 and FOSL-2, whose overexpression leads to enhanced tumour cell motility and invasion in breast cancer, colorectal cancer and mesothelioma, were not regulated by CBX7 (data not shown)." (PMID 24865347, 2014). "In fact, the DNB method reveals the existence of the pre-transition state, which, however, may not be detected by molecules such as EGR4, FOSL-1, FHL2, and DIPA, although these four transcription factors are proved to be effective for indicating the differentiation of breast cancer cells." (PMID 26284108, 2015).
colorectal cancer (37 papers, 2008 to 2026). A primary or metastatic malignant neoplasm that affects the colon or rectum. "FOSL1 has been implicated in the development and progression of several types of cancer, including breast, lung, prostate, gastric, colorectal cancer, and glioma." (PMID 38791400, 2024). "FOSL1 is highly concentrated in cancer-associated fibroblasts (CAFs) obtained from colorectal cancer (CRC) tissues." (PMID 38791400, 2024). "Moreover, FOSL1-driven transcriptional networks show mechanistic overlap between IBD-associated colorectal cancer (CRC) and other inflammation-linked gastrointestinal cancers, such as pancreatic ductal adenocarcinoma (PDAC)." (PMID 42193998, 2026). "Additionally, FOSL1 has been demonstrated to promote the proliferation, invasion, migration, and epithelial-mesenchymal transition of colorectal cancer cells, and was significantly associated with poor prognosis." (PMID 39944827, 2025). "Fosl1: The elevated expression of Fosl1 in colorectal cancer (CRC) and colon cancer has been demonstrated to be associated with a poor prognosis." (PMID 40951343, 2025). "The emerging role of ubiquitin-specific peptidase 21 (USP21) in stabilizing Fra-1 (FOSL1) highlights its involvement in promoting colorectal cancer (CRC) metastasis." (PMID 39695128, 2024). "Taken together, FOSL1 is a prognostic factor in various types of cancer, including breast, lung, liver, and colorectal cancer." (PMID 38791400, 2024). "The inhibition of FOSL1 in colorectal cancer cells has been found to reduce the population of cancer stem cells and inhibit tumor growth." (PMID 38791400, 2024). "Exosome-transmitted FOSL1 is attributed to oxaliplatin resistance in colorectal cancer via activation of ITGB4." (PMID 38814534, 2024). "The levels of FOSL1 ectopic expression are correlated with the degree of local invasion, lymph node involvement, and liver metastases in patients with colorectal cancer (CRC)." (PMID 38791400, 2024). "In colorectal cancer, FOSL1 promote migration and invasion by maintaining cancer cells in a mesenchymal-like state and has further been linked to poor DFS." (PMID 35562738, 2022). "For instance, FOSL1 upregulation led to the tumorigenesis of head and neck squamous cell carcinoma, and FOSL1 promoted the proliferation of colorectal cancer cells." (PMID 35484574, 2022). "In colorectal cancer cells, FOSL1 was also shown to promote cancer aggressiveness through EMT by direct transcription regulation of EMT-related genes." (PMID 34399888, 2021). "A previous report showed that IL-6/STAT3 inflammatory signaling axis induces the deacetylation of FOSL1 at the Lys-116 residue located within its DNA binding domain, leading to the increase of FOSL1 transcriptional activity and acquisition of colorectal cancer (CRC) stem-like properties (stemness)." (PMID 37642779, 2023). "It has been shown that FOSL1 can promote the development and invasion of colorectal cancer through the Smurf1-mediated FBXL2/Wnt/β-catenin axis and the migration, invasion, and proliferation of breast, head, and neck squamous cell carcinoma, pancreatic cancer, bladder cancer, and prostate cancer." (PMID 36061185, 2022). "After subjecting colorectal cancer cell lines (SW480 and SW620) to X-ray or c-ion radiation, the expression level of FOSL1 remarkably decreases." (PMID 38791400, 2024). "In addition to promoting EMT features, IL-6 induces stem-like properties in colorectal cancer cells, such as the expression of CSC markers CD44+/CD133+, the formation of spheroids, and increased drug-resistance, through FOSL1-dependent pathways." (PMID 38791400, 2024). "Notably, the FOSL1 intronic enhancer is a component of a significantly bigger Super Enhancer (SE) region, which has been discovered through comprehensive genome-wide investigations in GBM, pancreatic, and colorectal cancer cells." (PMID 38791400, 2024).
colorectal cancer (continued). "Notably, the FOSL1 intronic enhancer is part of a much larger SE (Super Enhancer) region, identified by genome-wide analyses in glioblastoma multiforme (GBM), pancreatic, and colorectal cancer cells." (PMID 35326630, 2022). "Moreover, the role of FOSL1 in EMT has been documented in breast and colorectal cancers." (PMID 34399888, 2021).
melanoma (36 papers, 2010 to 2026). A malignant, usually aggressive tumor composed of atypical, neoplastic melanocytes. "To investigate the functional relevance of FOSL1 in melanoma cell proliferation and motility, we performed loss-of-function assays in A375 and MEWo cell lines with two distinct shRNAs targeting FOSL1 (sh-FOSL1–1 and sh-FOSL1-2)." (PMID 41383633, 2025). "In melanoma, sustained expression of FOSL1 was associated with continuous overactivation of the MAPK pathway." (PMID 38957390, 2024). "In particular, Fra-1 (encoded by the gene FOSL1) is important for melanoma progression as its accumulation triggers the transcription factor switch that drives (partial)-EMT, downregulating Zeb2 and SNAI2 and directly upregulating Zeb1 at its promoter." (PMID 37181747, 2023). "Among the genes identified, the protein encoded by FOSL1 constitutes an interesting candidate with a potential effect on melanoma biology." (PMID 20663135, 2010). "Indeed, silencing FOSL1, i.e., the gene encoding Fra1, decreases pERK1/2 expression, as well as the proliferation rate in A375 and A2058 melanoma cells." (PMID 35163570, 2022). "Also, the FOS Like 1, AP-1 Transcription Factor Subunit (FRA-1), an AP-1 family member whose expression has been associated with melanoma progression, was virtually abrogated." (PMID 29484133, 2018). "In conclusion, we identified a distinct, predicted-immunoregulatory IGFBP3+ melanoma cell subtype and established FOSL1 as a key oncogenic driver within this subtype." (PMID 41383633, 2025). "Functional experiments have established that FOSL1 is an essential determinant in promoting the fundamental malignant characteristics of melanoma." (PMID 41383633, 2025). "Concerning the FOSL1 gene, our results show that in three melanoma cells, miR-34a-5p directly regulates its expression by binding to the 3’UTR region." (PMID 40869968, 2025). "Aberrant expression of FOSL1 has been recorded in melanoma cell lines, suggesting its possible involvement in melanoma development." (PMID 41383633, 2025). "FOSL1 knockdown significantly increased apoptosis and decreased melanoma cell motility and proliferation in vitro." (PMID 41383633, 2025). "According to research, FOSL1 expression is significantly higher in melanoma patient samples than nevi, and this higher level of expression is related to shorter patient survival." (PMID 41383633, 2025). "We identified immunoregulatory C2 IGFBP3+ melanoma cell subtypes in our investigation, and FOSL1 was a crucial transcription factor that aided in cell migration, proliferation, and survival." (PMID 41383633, 2025). "FOSL1, a significant part of the AP-1 transcription factor family, has attracted a lot of attention because of its role in the progression of melanoma." (PMID 41383633, 2025). "Although our study establishes strong links between the C2 type and FOSL1 in the development and immunomodulation of melanoma, there are limitations to our research." (PMID 41383633, 2025). "This research examined the heterogeneity of tumor cells in melanoma at the single-cell level, highlighting the significant involvement of FOSL1." (PMID 41383633, 2025). "Module M4 contained regulators such as FOSL1 that are associated with C1 melanoma CDH19 and C0 melanoma BIRC7." (PMID 37435067, 2023). "Critically, Maurus and others demonstrated that FOSL1 promotes anoikis resistant growth of melanoma cells on soft agar, and allows subcutaneous tumour growth in vivo via a Fra-1 target gene product, the chromatin modifier HMGA1." (PMID 37181747, 2023). "Teutschbein and colleagues discovered that FOSL1 had increased expression levels in human melanoma cell lines when compared to human melanocytes, whereas FOSL1 reduction in human melanoma cell lines also reduced migration and proliferation." (PMID 35202347, 2022).
melanoma (continued). "As FOSL1 (Fra-1) links the BRAF/NRAS pathway to TWIST (see Discussion below), we chose to verify the microarray results from the xenograft experiment in the patients’ melanoma samples by staining for FOSL1." (PMID 30089785, 2018). "All dedifferentiated mouse melanoma cell lines (HCmel3-Rs and HCmel10) expressed low amounts of MITF and its targets, but high levels of c-Jun/Fosl1, showing that the MITFlow/c-Junhigh cell state is conserved in mouse melanomas." (PMID 26530832, 2015). "The expression of these genes was also monitored in human melanoma cell lines, and the target gene FOSL1 was knocked down by siRNA." (PMID 20663135, 2010). "We furthermore found that the knockdown of FOSL1 reduced proliferation and migration of human melanoma cell lines." (PMID 20663135, 2010). "To investigate the effect of FOSL1 on melanoma growth, we downregulated FOSL1 in the melanoma cell lines A375 and Mel Juso using siRNA." (PMID 20663135, 2010). "In our study, FOSL1 protein levels were not only upregulated in mouse melanocytes expressing HERmrk, but were also elevated in human melanoma cell lines compared to the human melanocyte cell line Hermes3a and NHEM cells." (PMID 20663135, 2010). "At the level of protein, NHEM displayed almost no expression of most of the proteins, whereas in the majority of examined melanoma cell lines FOSL1, IGFBP3 and DUSP4 were strongly expressed." (PMID 20663135, 2010). "Recently, B-RAFV600E-dependent genes were analysed by MEK inhibition or BRAF siRNA in human melanoma cell lines, revealing regulation of the transcription factors FOSL1 and EGR1 by this pathway." (PMID 20663135, 2010). "Precision treatments for melanoma may be advanced by focusing on the FOSL1 or C2 subtype pathways, which may assist in overcoming immunotherapy resistance." (PMID 41383633, 2025). "Furthermore, FOSL1 can affect Cyclin E or regulate apoptosis-related proteins to promote melanoma cell proliferation." (PMID 41383633, 2025). "Since the overexpression of genes such as AXL and FOSL1 plays an important role in resistance to traditional therapies in melanoma and other types of tumors, part of the scientific research has focused on the regulatory mechanisms activated upstream by non-coding RNAs." (PMID 40869968, 2025). "Knockdown of FOSL1 in human melanoma cell lines reduced cell proliferation and migration." (PMID 29416636, 2018). "High FOSL expression in the melanoma was correlated with shortened patient survival (age-adjusted HR 3.2, 95%-CI [1.1;9.1]; p = 0.029) with a 5-year survival of 68.0% (95%-CI [56.4;77.1]) in comparison to 85.7% (95%-CI [66.3;94.4]) for the FOSL1 low patients." (PMID 30089785, 2018). "Next, we addressed whether there is a direct mechanistic link between MITF and c-Jun/FOSL1 that explains their anti-correlated expression found in melanoma cell line panels." (PMID 26530832, 2015). "Knockdown of FOSL1 in human melanoma cell lines reduced their proliferation and migration." (PMID 20663135, 2010). "By knocking down FOSL1, we could demonstrate a pro-proliferative and pro-migratory function of this protein in melanoma cell lines." (PMID 20663135, 2010). "Thus, this study reveals FOSL1 as new potential molecular player in melanomagenesis by using the Xmrk melanoma model." (PMID 20663135, 2010). "Moreover, FOSL1 may augment the migratory and invasive characteristics of melanoma cells by activating pertinent signaling pathways including the PI3K-Akt pathway." (PMID 41383633, 2025). "Additionally, flow cytometry utilizing Annexin V/PI labeling demonstrated an elevation in apoptotic cell populations subsequent to FOSL1 silencing, suggesting that FOSL1 may play a role in the survival of melanoma cells." (PMID 41383633, 2025).
melanoma (continued). "Prior research has shown that inhibiting FOSL1 expression via gene editing methods or small molecule inhibitors in cellular and animal models, markedly hinders the proliferation, migration and invasive potential of melanoma cells, while also diminishing tumor growth and metastasis." (PMID 41383633, 2025). "Investigating whether FOSL1 knockdown alters the expression profile of nerves or neuroimmune signaling molecules could reveal novel neuro-immunomodulatory functions of this oncogenic TF in melanoma." (PMID 41383633, 2025). "FOSL1 expression could be investigated by immunohistochemistry in melanoma from 106 patients." (PMID 30089785, 2018). "Importantly, we also could demonstrate a pro-tumorigenic role of FOSL1 in human melanoma cell lines, thus confirming the Xmrk oncogene as instrumental in the search of new melanoma players." (PMID 20663135, 2010). "Furthermore, c-JUN, which might be a potential binding partner for FOSL1 in the AP-1 complex, is highly expressed in most melanoma and is required for tumor transformation." (PMID 20663135, 2010). "Another AP-1 family member, Fra1 (FOSL1), downregulates MITF through its transcriptional target, the chromatin modifier HMGA1, and induces the expression of AXL, driving melanoma cells to the MITFlow/AXLhigh state." (PMID 34604096, 2021). "ERK activation results in phosphorylation (pFRA1) and induction of the transcription factors, FRA1/FOSL1 and MYC, which are critical for melanoma development, progression, and resistance." (PMID 33122628, 2020). "High FOSL1 and altered TWIST1 expression were found to be correlated with shortened survival in the cohort of melanoma patients." (PMID 30089785, 2018). "High expression of CEACAM1 in the melanoma samples correlated with high FOSL1 (φ = 0.36, p < 0.001) and also CEACAM1 staining in a certain area of an individual melanoma often correlated with FOSL1 staining intensity in the same area (serial sections)." (PMID 30089785, 2018). "The markers CEACAM1, FOSL1, IGFBP7, LXN and cytoplasmic/nuclear TWIST were used as predictors in a multivariate Cox model (adjusted for age) for the prognosis of the melanoma patients’ survival." (PMID 30089785, 2018). "Realtime PCR revealed a significantly higher expression of FOSL1, OPN, IGFBP3, DUSP4 and TAAL6 in most of the melanoma cell lines compared to normal melanocytes." (PMID 20663135, 2010). "Importantly, we found that FOSL1, OPN, IGFBP3, DUSP4, and TAAL6 also exhibited increased expression levels in human melanoma cell lines compared to human melanocytes." (PMID 20663135, 2010). "Its function in melanoma was not described previously, but pro-tumorigenic roles of FOSL1 were reported for other solid cancers." (PMID 20663135, 2010). "Interestingly, FOSL1 (FOS like 1, AP-1 transcription factor subunit) was considered as a potential highly expressed protein in a mild EMN group involved in melanocytes cell and related melanoma." (PMID 35202347, 2022). "We also found that although some established YAP/TAZ target genes (CRIM1, F3, ANKRD1) correlated strongly with CTGF and CYR61 expression in human melanoma, others did not (WWC1, FOSL1, FSTL3)." (PMID 38473214, 2024).